CEBPA (CCAAT enhancer binding protein alpha)
Diseases named in the same sentence as CEBPA in open-access papers (continued):
Sharing a sentence is not in itself a finding about the gene and the disease.
Glucose intolerance (2 papers, 2020 to 2024). Glucose intolerance (GI) can be defined as dysglycemia that comprises both prediabetes and diabetes. "Previous studies have shown that CEBPA-null mice exhibit glucose intolerance, decreased serum cholesterol levels, and hepatic steatosis." (PMID 38443583, 2024).
leukocytosis (2 papers, 2013 to 2019). "After that, the dependencies between leukocytosis, blast percentage in the bone marrow and CEBPA transcript level were evaluated." (PMID 31666608, 2019).
lymph node metastasis (2 papers, 2022). "Clinical specimen results confirmed that the risk model established was effective, and the different expression pattern of ASNS and CEBPA was correlated with TNM stage and lymph node metastasis, whilst that of CAD was correlated with post-operative tumor metastasis and recurrence." (PMID 35174151, 2022).
malaria (2 papers, 2014 to 2018). Malaria is a serious and sometimes fatal disease caused by a parasite that commonly infects a certain type of mosquito which feeds on humans. "In summary, an additional major inflammatory protein, CCAAT/Enhancer Binding protein-alpha (CEBPA) and three intracellular proteins were found with increased levels in plasma from all malaria-positive groups." (PMID 24743550, 2014). "Six representative examples, showing both increased (ADSSL1, CEBPA, CRP, LBP) and decreased protein levels (CCL5, SPARC) in malaria patients compared to controls are shown in." (PMID 30442134, 2018). "Changes in levels due to inflammation, as shown with CEBPA, CRP and CCL5 protein levels, were more exacerbated in the CM than the DC samples suggesting a stronger inflammatory response in malaria-infected patients than in other diseases." (PMID 24743550, 2014).
myocardial ischemia (2 papers, 2015 to 2024). A disorder of cardiac function caused by insufficient blood flow to the muscle tissue of the heart. "On the other hand, we found that aging increased the differentiation capacity of SAT-ASCs and TAT-ASCs from patients with myocardial ischemia rather than decrease it, as shown by the increased levels of the adipogenic markers, ADRP and CEBPα, in cells from elderly subjects." (PMID 26657132, 2015).
non-small cell lung carcinoma (2 papers, 2013 to 2022). A group of at least three distinct histological types of lung cancer, including non-small cell squamous cell carcinoma, adenocarcinoma, and large cell carcinoma. "Unlike hematopoietic malignancies, in which the CEBPA gene has been demonstrated to be mutated, CEBPA mutations are rare in non-small cell lung cancer (NSCLC)." (PMID 23437297, 2013). "Notably, CEBPA expression is frequently down-regulated in human non-small cell lung cancer due to promoter methylation or genetic deletion." (PMID 35228570, 2022).
oral squamous cell carcinoma (2 papers, 2015 to 2025). "It has been reported that CEBPA is positively related to chemoresistance and that CEBPA overexpression can significantly enhance chemoresistance in oral squamous cell carcinoma (OSCC)." (PMID 40297811, 2025).
osteosarcoma (2 papers, 2018 to 2021). A usually aggressive malignant bone-forming mesenchymal neoplasm, predominantly affecting adolescents and young adults. "The expression forced of CEBPα obligates 3T3-L1 pre-adipoblasts to adipocyte differentiation and induces cell-cycle arrest, and also the antiproliferation activity of CEBPα encompasses to hepatocytes and Saos2 osteosarcoma cells have been described." (PMID 29911120, 2018).
renal cell carcinoma (2 papers, 2025). "It was shown that renal cell carcinoma (RCC) patients’ urine EVs included lower levels of mRNA for pterin-4 alpha-carbinolamine dehydratase-1 (PCBD1), glutathione transferase alpha 1 (GSTA1), and CCAAT enhancer binding protein alpha (CEBPA) than controls." (PMID 40305328, 2025).
schizophrenia (2 papers, 2020 to 2024). A major psychotic disorder characterized by abnormalities in the perception or expression of reality. "We also appraised the diagnostic power of transcript quantities of CHAST, CEBPA, DICER1-AS1, H19 and HNF1A-AS1 in distinguishing between patients with schizophrenia and controls through depicting ROC curves." (PMID 33093650, 2020). "Next, we appraised the diagnostic power of transcript quantities of CHAST, CEBPA, DICER1-AS1, H19 and HNF1A-AS1 in distinguishing between patients with schizophrenia and controls through depicting ROC curves." (PMID 33093650, 2020).
allergic disease (1 paper, 2025). An immune response that occurs following re-exposure to an innocuous antigen, and that requires the presence of existing antibodies against that antigen. "GWAS data further strengthen the link between these genes and diseases, with BATF, CEBPA, and ETS1 associated with allergic diseases, and PTPN22, ETS1, PTPN11, and BATF linked to RA." (PMID 40839671, 2025).
chronic hepatitis C (1 paper, 2017). "We previously reported that CEBPα was induced in the liver of chronic hepatitis C patients who were treated with peretinoin." (PMID 28591717, 2017).
chronic lung disease (1 paper, 2024). According to the definitions of the American and British Thoracic Societies, including pulmonary functional tests, X-rays, and CT scans for items such as fibrosis, bronchiectasis, bullae, emphysema, nodular or lymphomatous abnormalities. "In the future, such an approach could be harnessed to rescue expression of CEBPA or other regulators of aberrant epithelial cell types in patients with IPF and other chronic lung diseases, to restore tissue homeostasis and promote lung repair." (PMID 39012710, 2024).
chronic neutrophilic leukemia (1 paper, 2019). A rare chronic myeloproliferative neoplasm characterized by neutrophilic leukocytosis. "CSF3R mutations are associated with chronic neutrophilic leukemia (defined by an abundance of mature neutrophils) yet also accelerate AML formation in the context of mutant CEBPA." (PMID 31784538, 2019). "Conversely, however, it is possible that CEBPA mutations could be acquired late during blast-crisis transformation of chronic neutrophilic leukemia." (PMID 31784538, 2019).
epithelial ovarian tumor (1 paper, 2022). "CEBPA might be involved in the proliferation process of epithelial ovarian tumor cells in vivo, which could play an important role as an early molecular event." (PMID 35284484, 2022).
erythroleukemia (1 paper, 2016). Acute erythroid leukemia characterised by the presence of at least 50% erythroid precursors and at least 20% myeloblasts in the bone marrow. "However, absence of C/EBPα results in loss of myeloid identity in transgenic mice with BCR-ABL1-induced CML-like disease and, interestingly, causes erythroleukemia instead, suggesting that CEBPα is essential for BCR-ABL1-positive CML." (PMID 27233483, 2016).
gliosarcoma (1 paper, 2018). A rare histological variant of glioblastoma (WHO grade IV) characterized by a biphasic tissue pattern with alternating areas displaying glial and mesenchymal differentiation (WHO). "Significantly downregulated transcription factors common to both gliosarcomas were HOXA5, FOXO1, and CEBPA." (PMID 29416795, 2018). "Examination of another secondary gliosarcoma culture in our collection, SGS2, similarly showed significant downregulation of CEBPA and FOXO1." (PMID 29416795, 2018).
glucose metabolism disorder (1 paper, 2020). "The most significantly affected networks were ‘glucose metabolism disorder’ and ‘transport of lipids’ and within these networks we identified three transcriptional factors being involved, i.e. FOX A2, CEBPA and PPARA." (PMID 32764569, 2020).
Hypertension (1 paper, 2024). The presence of chronic increased pressure in the systemic arterial system. "Among the 123 mRNAs associated with hypertension, only the CEBPA transcription factor gene was identified." (PMID 38836231, 2024).
hypospadias (1 paper, 2025). Hypospadias is the displacement of the urethral meatus on the ventrum of the penis. "In the current study, we explored the effect of MAFB, CEBPA, and Wnt/β-catenin signaling in the pathogenesis of hypospadias." (PMID 39569391, 2025). "In conclusion, our present work reported CEBPA as a novel gene involved in the pathogenesis of hypospadias." (PMID 39569391, 2025). "Moreover, MAFB and CEBPA expression were reduced in the prepuce tissues of hypospadias patients." (PMID 39569391, 2025).
insulinomas (1 paper, 2021). "In our studied samples of micro-tumors, we have not found alteration in MEN1, but gain status in IRS2, FOXL2 and CEBPA genes was found, suggesting that they can play a role in the development of micro- to macro-tumors, to wit insulinomas, and, accordingly, insulinomatosis." (PMID 34737724, 2021). "Copy number alterations involving FOXL2, IRS2, CEBPA and ATRX genes were observed in insulinoma as well as in micro-tumors samples, suggesting that alterations of these genes may promote malignization in the β-cells population." (PMID 34737724, 2021).
keloid (1 paper, 2025). An irregularly shaped, elevated mark on the skin caused by deposits of excessive amounts of collagen during wound healing. "lnc-LSP1P5, a known lncRNA, resulted more elevated in the nuclei of fibroblasts in keloids, and it seems to silence CEBPA, which is an antifibrotic factor." (PMID 41007836, 2025).
lupus (1 paper, 2020). "Accordingly, we found differentially methylated regions from lupus HSPCs overlapping with transcription factor binding sites relevant to haematopoietic development, including Cebpα (data not shown)." (PMID 31780527, 2020).
Lymphadenopathy (1 paper, 2009). Enlargement (swelling) of a lymph node. "Patients with a CEBPα mutation have higher hemoglobin levels, lower platelet counts, higher blast counts, and are less likely to present with lymphadenopathy or extramedullary leukemia compared to patients without a CEBPα mutation." (PMID 19490647, 2009).
meningoencephalitis (1 paper, 2023). Inflammation of the meninges and brain, generally secondary to an infectious cause. "In conclusion, CEBPα promotes pyroptosis in meningoencephalitis induced by A. cantonensis infection by activating miR-101b-3p expression." (PMID 36747241, 2023).
monocytopenia (1 paper, 2025). "Although both neutrophils and monocytes harbor UBA1 mutations, in the marrow, there is a differentiation bias towards neutrophils over monocytes with increased expression in the CEBPA master transcription factor and decreased expression in IRF810; with notable monocytopenia in 30% of patients." (PMID 40394087, 2025).
rectal cancer (1 paper, 2025). A primary or metastatic malignant neoplasm that affects the rectum. "Interestingly, a 44-year-old patient carrying a germline CEBPA variant died of rectal cancer, without prior AML treatment." (PMID 40313597, 2025).
rheumatoid arthritis (1 paper, 2024). A chronic, systemic autoimmune disorder characterized by inflammation in the synovial membranes and articular surfaces. "Besides, in the rheumatoid arthritis, the AUC values for CEBPA, CEACAM1, BTG3, and IL1R1 were 0.609, 0.730, 0.686, and 0.608, respectively and diagnostic model achieved a high AUC of 0.844 on this cohort." (PMID 39113685, 2024).
T-cell leukemia (1 paper, 2013). A malignant disease of the T-lymphocytes in the bone marrow, thymus, and/or blood. "Interestingly, previously published microarray data showed that the CEBPA gene was overexpressed in adult T-cell leukemia cells." (PMID 24359396, 2013).
trisomy 8 (1 paper, 2022). "It is usually associated with other chromosomal abnormalities, particularly trisomy 8, and other genetic mutations, such as FLT3-ITD, WT1, and CEBPA, and appears to play a role in histone methylation and acetylation." (PMID 35740427, 2022).
tumor (218 papers, 1999 to 2026). "This factor has been identified as a tumor suppressor, with mutations or downregulation of its encoding gene (CEBPA) expression recognized as pivotal contributors to oncogenesis and progression of various cancers." (PMID 38965606, 2024). "The first study was published in 2001, reporting that CEBPA mutations were identified in 10 of 137 patients with AML, which was also the first report showing CEBPA mutations in human neoplasia." (PMID 35178345, 2022). "Over expressions of tumor suppressive miR-181 family were found in CEBPA-mutated cases and has been showed to correlate with treatment response and better clinical outcome in AML patients." (PMID 28380436, 2017). "Genes previously associated with neoplasia, CEBPA and SDHD, were decreased in expression (-1.5 – -2, p < 0.02)." (PMID 25023465, 2014). "This aligns with existing literature indicating that CEBPA mutations may facilitate immune cell recruitment and tumor microenvironment remodeling, thereby influencing prognosis across various cancer types." (PMID 40372586, 2025). "In addition, KDM6B acts as a tumor suppressor in PC by demethylating histone H3 lysine 27, thereby controlling the expression of CEBPA, a key gene associated with cancer progression." (PMID 39239542, 2024). "In contrast to CEBPA, an increase in CEBPB expression has been associated with worse oncological outcomes in several tumor types including prostate, breast, and colon." (PMID 40226120, 2025). "In another case, SJ032178, WGS and WTS identified an acquired frameshift variant in the N-terminal transactivation domain of CEBPA, with a VAF of 35% in genomic DNA and 97% in WTS, respectively, indicating exclusive expression of the mutant allele in tumor." (PMID 41057686, 2025). "Strikingly, further KO of CEBPA rescued tumour growth, even further promoted tumour growth greater than control, and DACH1 KO also performed similarly." (PMID 38797942, 2024). "Xenograft tumor mouse experiments revealed that CEBPA knockdown in HuH-7 cells dramatically decreased tumor volume and tumor weight." (PMID 39267787, 2024). "First, we determined that ChromVAR‐inferred binding of transcription factors important for driving myeloid cell development (such as SPI1 and CEBPA) were more significantly more prevalent in tumour than benign pancreata." (PMID 38426634, 2024). "We found that CEBPA KO and DACH1 KO effectively reversed the reduced tumour cell functions caused by miR‐31 KO." (PMID 38797942, 2024). "Mina Therapeutics developed MTL-CEBPA, a nanoformulated small double-stranded 2′-O-methylated RNA that can specifically activate the expression of the tumor suppressor CEBPA, preventing activation of Wnt/β-catenin signaling." (PMID 39065798, 2024). "MiR‐31 in turn facilitates β‐catenin stabilisation via directly repressing tumour suppressors CEBPA and DACH1, which direct the expression of multiple essential Wnt/β‐catenin pathway inhibitors." (PMID 38797942, 2024). "Studies have shown that therapeutic upregulation of CEBPA leads to inactivation of immunosuppressive myeloid cells and has effective anti-tumor responses in different tumor models and cancer patients." (PMID 39712244, 2024). "Loss-of-function mutations of CEBPA contribute to ~10% of AML development, consistent with a tumour suppressor role." (PMID 37019911, 2023). "As a tumor suppressor, CEBPA is downregulated in multiple cancers, due to epigenetic regulation of DNA methylation." (PMID 38102722, 2023). "miR-486 was considered as a regulator of myeloid cell differentiation and apoptosis by targeting CEBPα, and the expression between miR-486 and CEBPα was inversely correlated in tumor-induced M-MDSCs (TM-MDSCs)." (PMID 35634311, 2022).
tumor (continued). "Results showed that in Group 1, the protein level of ASNS and CEBPA was higher in tumor tissues than in adjacent normal colon tissues, while in Group 2, the results were opposite." (PMID 35174151, 2022). "The results showed that the expression of ASNS was correlated with the size of tumor growth,that of CEBPA was correlated with the gender of patients and TNM stage of tumor, and that of CAD was highly correlated with recurrence and metastasis." (PMID 35174151, 2022). "CEBPA acts a crucial role in terminal differentiation, and has been proved to be a tumor suppressor gene in GC." (PMID 35421923, 2022). "Other studies, beyond the main scope of this review, aim to restore CEBPa function by blocking the CEBPa upstream suppressor RAC1 or by targeting the downstream CEBPa p30 tumor-promoting targets." (PMID 34359655, 2021). "The results showed that tumors with CEBPA knock down (simulate the 1p/19q codel tumor) can improve the inhibition of T cells on tumor cells." (PMID 34956239, 2021). "The MTL-CEBPA treated group had significant upregulation of CEBPA mRNA (1.74 fold, p = 0.0012) and the tumor regressing subgroup of anti-PD-1+MTL-CEBPA had a high expression of CEBPA mRNA (8.69 fold, p < 0.0001)." (PMID 34502076, 2021). "Immunohistochemical staining for differentiation-related markers of primary tumors derived from CNE1-TetOn-LMP1 and CNE1-TetOn-LMP1-IRES-CEBPA cells confirmed the differentiation of tumor tissues after CEBPA restoration." (PMID 34482361, 2021). "Immunohistochemical analysis revealed decreased CEBPA staining in tumor sections with LMP1 expression, compared with the control tumor sections." (PMID 34482361, 2021). "Our new findings show the fine tuning of OGA in HCC development by RANBP2 through the inactivation of CEBPα, and its function as a tumor suppressor is accordant with clinically relevant reports." (PMID 34298689, 2021). "Reconstitution of CEBPA expression by plasmid transfection or lentiviral transduction inhibited proliferation and migration of cancer cells and suppressed tumor growth and metastasis in vivo." (PMID 34770939, 2021). "We found CNE2 cells expressing CEBPA showed a significant reduction in tumor growth compared to control cells." (PMID 34482361, 2021). "By activating CEBPA in the HCC tumor microenvironment with a first-in-class small activating RNA oligonucleotide drug, MTL-CEBPA, white cell count significantly increases, and HCC progression delays in combination with Sorafenib treatment." (PMID 34336665, 2021). "Tumor suppressive effects of CEBPA saRNA are also demonstrated in preclinical models of pancreatic ductal adenocarcinoma." (PMID 34770939, 2021). "The results again showed that the mRNA levels of CEBPA were decreased in the tumor cells with LMP1 expression." (PMID 34482361, 2021). "Protein levels of CEBPA were examined in several tumor and normal nasopharyngeal epithelial cell lines of well differentiated to poorly differentiated status." (PMID 34482361, 2021). "An increase in CEBPA expression was confirmed in monocytic-MDSC (M-MDSC) and tumor-associated macrophage (TAM) populations isolated from the tumors of mice treated with MTL-CEBPA." (PMID 34770939, 2021). "CEBPA is a tumor suppressor and several mechanisms of CEBPA downregulation in cancer have been reported." (PMID 34770939, 2021). "Another example is the transcription factor CCAAT/enhancer-binding protein alpha (CEBPα), a tumor-suppressor protein which plays an important role for normal hepatocyte function." (PMID 31906510, 2020). "As determined by qRT-PCR, CEBPA expression was effectively increased in C/EBPα-tumor organoids compared with control organoids." (PMID 32034145, 2020). "Here, the authors perform an in vivo shRNA screen in a CEBPA mutant AML mouse model and identify that RBM25 controls the splicing of pre-mRNAs encoding BCL-X and BIN1 to exert its tumour suppressor activities in AML." (PMID 30635567, 2019).